HRG (histidine rich glycoprotein)
Description:
Plasma glycoprotein that binds a number of ligands such as heme, heparin, heparan sulfate, thrombospondin, plasminogen, and divalent metal ions. Binds heparin and heparin/glycosaminoglycans in a zinc-dependent manner. Binds heparan sulfate on the surface of liver, lung, kidney and heart endothelial cells. Binds to N-sulfated polysaccharide chains on the surface of liver endothelial cells. Inhibits rosette formation. Acts as an adapter protein and is implicated in regulating many processes such as immune complex and pathogen clearance, cell chemotaxis, cell adhesion, angiogenesis, coagulation and fibrinolysis. Mediates clearance of necrotic cells through enhancing the phagocytosis of necrotic cells in a heparan sulfate-dependent pathway. This process can be regulated by the presence of certain HRG ligands such as heparin and zinc ions. Binds to IgG subclasses of immunoglobins containing kappa and lambda light chains with different affinities regulating their clearance and inhibiting the formation of insoluble immune complexes. Tethers plasminogen to the cell surface. Binds T-cells and alters the cell morphology. Modulates angiogenesis by blocking the CD6-mediated antiangiongenic effect of thrombospondins, THBS1 and THBS2. Acts as a regulator of the vascular endothelial growth factor (VEGF) signaling pathway; inhibits endothelial cell motility by reducing VEGF-induced complex formation between PXN/paxillin and ILK/integrin-linked protein kinase and by promoting inhibition of VEGF-induced tyrosine phosphorylation of focal adhesion kinases and alpha-actinins in endothelial cells. Also plays a role in the regulation of tumor angiogenesis and tumor immune surveillance. Normalizes tumor vessels and promotes antitumor immunity by polarizing tumor-associated macrophages, leading to decreased tumor growth and metastasis.
Synonyms: HPRG; HRGP; THPH11
Tractability: Antibody: UniProt places it where antibodies can reach, with high confidence; its Gene Ontology location is reachable by antibodies, with high confidence; UniProt predicts a signal peptide or a membrane-spanning region. PROTAC: its protein half-life has been measured.
Gene: Protein-coding gene on chromosome 3 (186,660,216 to 186,678,452, forward strand). Ensembl gene ENSG00000113905.
Subcellular location: Secreted
Pathways (Reactome):
Hemostasis: Dissolution of Fibrin Clot; Platelet degranulation
Immune System: Regulation of FXIIa and plasma kallikrein activity
Gene Ontology:
Molecular function: heme binding; heparan sulfate proteoglycan binding; heparin binding; immunoglobulin binding; metal ion binding; protein binding; signaling receptor binding; zinc ion binding; serine-type endopeptidase inhibitor activity; cysteine-type endopeptidase inhibitor activity
Biological process: antimicrobial humoral immune response mediated by antimicrobial peptide; defense response to fungus; negative regulation of angiogenesis; negative regulation of cell adhesion; negative regulation of cell adhesion mediated by integrin; negative regulation of cell growth; negative regulation of cell population proliferation; negative regulation of endothelial cell chemotaxis; negative regulation of lamellipodium assembly; negative regulation of vascular endothelial growth factor signaling pathway; platelet activation; positive regulation of apoptotic process; positive regulation of blood vessel remodeling; positive regulation of focal adhesion assembly; positive regulation of immune response to tumor cell; regulation of actin cytoskeleton organization; regulation of blood coagulation; regulation of gene expression; negative regulation of blood vessel endothelial cell migration; negative regulation of fibrinolysis; regulation of platelet activation
Cellular component: blood microparticle; cell surface; extracellular exosome; extracellular matrix; extracellular region; plasma membrane; platelet alpha granule lumen
Genetic constraint (gnomAD): Loss-of-function variants: 14 observed, 17 expected, observed/expected ratio (o/e) 0.82, 90% interval 0.54 to 1.29. The upper end of that interval is the gene's LOEUF score, 1.29, which puts it in group 5 of 6, group 1 being the genes least tolerant of losing a copy. Missense variants: 572 observed, 575.47 expected, observed/expected ratio (o/e) 0.99, 90% interval 0.93 to 1.07. Synonymous variants: 206 observed, 215.57 expected, observed/expected ratio (o/e) 0.96, 90% interval 0.85 to 1.07.
Gene-disease validity (ClinGen):
ClinGen rates the evidence that HRG causes each of these diseases.
hereditary thrombophilia due to congenital histidine-rich (poly-L) glycoprotein deficiency (autosomal dominant): Moderate.
Homologues: Orthologues: chimpanzee HRG (97% identical), macaque HRG (91% identical), pig HRG (65% identical), rabbit HRG (63% identical), rat Hrgl1 (61% identical), mouse Hrg (61% identical), rat Hrgl1 (60% identical), guinea pig HRG (53% identical), dog HRG (47% identical), zebrafish fetub (22% identical), tropical clawed frog hrg (19% identical), tropical clawed frog MGC69493 (18% identical), and 1 more. Paralogues in human: FETUB (18% identical), KNG1 (17% identical), AHSG (15% identical).
Diseases named in the same sentence as HRG in open-access papers:
HRG is named in the same sentence as 74 diseases in open-access papers, as found by Europe PMC text mining. Sharing a sentence is not in itself a finding about the gene and the disease. The quoted sentences say what the papers report.
breast carcinoma (16 papers, 2010 to 2024). "Disruption of HRG function is associated with various diseases, including breast cancer and hepatocellular carcinoma." (PMID 39896931, 2024). "CCL2 production has been reported to be more inducible in HER2+/ER− breast carcinoma cells compared with HER2+/ER+ cells under EGF/HRG stimulation, and enhanced NF-κB transcription levels were detected in HER2+/ER− breast carcinoma cells." (PMID 34386431, 2021). "Binding of A30 to HER3 inhibited HRG-dependent tyrosine phosphorylation of HER2 and the HRG-induced growth response of MCF7 breast cancer cells in vitro." (PMID 29562664, 2018). "Taken together, HRG-β1 induced EMT through phospho-Smad2-mediated expression of Snail via the PI3k/Akt signaling pathway in both breast cancer cell lines." (PMID 23937725, 2013). "HRG is a ligand for ErbB3 and ErbB4 and has also been reported to promote the invasive behavior of breast cancer cells in vitro." (PMID 23937725, 2013). "Additionally, Skp2 knockdown suppressed glucose uptake and glycolysis by reduced Glu1 transcription and protein expression in breast cancer cells upon EGF or HRG stimulation, repressing breast cancer development." (PMID 34068643, 2021). "Blockade of HRG expression inhibits tumorigenesis and metastasis of breast cancer cells." (PMID 23937725, 2013). "In this study, we have obtained evidence that HRG plays an important role in breast cancer." (PMID 23937725, 2013). "This may have particular relevance to tumor angiogenesis since HRG has been shown localize in the stromal connective tissue of human tumors, including breast cancer and glioblastoma, and to mask the TSR domain of TSP." (PMID 22808089, 2012). "In addition, HRG transcripts have been detected in the tumor microenvironment of breast cancer." (PMID 35847718, 2020). "In addition to the mRNA reduction of classical breast cancer subtype markers, expression of ERBB receptor family members HER3 and HER4, as well as the major ligands associated with all major ERBB family signaling molecules (EGF, BTC, HRG) were reduced." (PMID 26522776, 2015). "Third, ligand-mediated activation of ERBB3 has been shown to result in PI3K/AKT-mediated resistance to TKIs in a variety of cancers, including ERBB2-amplified breast cancer cells stimulated with ERBB3 ligands, NRG1 or HRG." (PMID 34675407, 2022). "We found that pterostilbene was able to suppress HRG-β1-mediated cell invasion, motility and cell transformation of MCF-7 human breast carcinoma through down-regulation of matrix metalloproteinase-9 (MMP-9) activity and growth inhibition." (PMID 19617202, 2011). "In this study, which will be referred to here as the HER2 dataset, the authors were interested in the signaling response downstream of EGF and HRG and in response to HER2 amplification, which is common to several breast cancers." (PMID 21799663, 2011). "HRG is known to induce Rac1 activation and subsequent phosphorylation of p21 (RAC1)-activated kinase 1 (PAK1), a critical effector protein of Rac1 signaling, in breast cancer cells." (PMID 29534468, 2018).
Sepsis (11 papers, 2009 to 2025). Sepsis is defined as life-threatening organ dysfunction caused by a dysregulated host response to infection. "Of note, HRG has been reported to suppress sepsis and tumor metastasis, inhibit hyperinflammation in acute pancreatitis, and relieve liver ischemia/reperfusion injury." (PMID 39148004, 2024). "Previously, we revealed that plasma HRG levels were markedly decreased due to a rapid reduction in HRG mRNA expression in the liver, deposition of HRG on immunothrombi, and degradation of HRG by thrombin in a sepsis state." (PMID 36989333, 2023). "HRG is a 75 kDa glycoprotein synthesized in the liver and released into the bloodstream to modulate sepsis-related biological reactions by binding to several substances (like heparin, factor XII, fibrinogen, thrombospondin, IgG, C1q, among others) and cells." (PMID 36430174, 2022). "We previously reported that plasma histidine-rich glycoprotein (HRG) levels decreased in septic mice, and supplemental infusion of HRG improved survival in mice model of sepsis." (PMID 33986340, 2021). "Some of these affected proteins changed in a different direction for NEC and sepsis (e.g., HRG), but more studies are required to identify NEC- and sepsis-specific biomarkers." (PMID 33133078, 2020). "We propose that decreases in the plasma protein histidine-rich glycoprotein (HRG) is an excellent biomarker of sepsis compared with the current markers." (PMID 30119699, 2018). "Based on the novel pathophysiological roles of HRG in the cascade of events during sepsis, we also discuss the potential for supplemental therapy with purified HRG." (PMID 30119699, 2018). "Among these are acute-phase reactants such as platelet factor 4, histidine-rich glycoprotein, vitronectin, fibronectin and lipopolysaccharide-binding protein, which increase in sepsis." (PMID 19958532, 2009). "HRG also plays a significant role in modulating immune responses and angiogenesis, demonstrating potential in clinical applications for tumor targeting and sepsis-related immune regulation." (PMID 40171266, 2025). "Decrease in histidine-rich glycoprotein (HRG) was reported as a cause of dysregulation of the coagulation-fibrinolysis and immune systems, leading to multi-organ failure, and it may be a biomarker for sepsis, ventilator-associated pneumonia, preeclampsia, and coronavirus disease 2019." (PMID 35858852, 2022). "In addition, our previous study found that the knockdown of liver HRG by siRNA could exacerbate septic inflammation and lethality compared with that in the control mice, which indicated that the depletion of HRG are more vulnerable to sepsis." (PMID 32498020, 2020).
lung carcinoma (9 papers, 2017 to 2022). "For example, decreased expression of HRG was observed in advanced lung cancer and is associated with the disease stage." (PMID 33553172, 2020). "In tumor tissue from the cancer genome atlas (TCGA), high expression of HRG is seen in liver cancer as well as in rare cases of lung cancer and renal cancer." (PMID 35847718, 2020). "Finally, to consolidate these in vitro and in vivo findings, we investigated the plasma levels of S100A8/A9 and HRG in clinical patients who suffered from brain metastasis of lung cancer." (PMID 36142212, 2022). "HRG gene levels are decreased in advanced lung cancer and the gene is known to have antifibrinolytic properties that support its detected low levels in MV samples, which may indicate the progression of lung fibrosis." (PMID 35271646, 2022). "Finally, in vitro experiments to better characterize the function of HRG in lung cancer patients, including HRG binding to heparin and fibrin clots, should be performed in the future." (PMID 30944671, 2019). "When tested clinically in ovarian, breast and lung cancer, HRG mRNA expression was found to be both potentially prognostic of insensitivity to standard therapy and potentially predictive of benefit from the addition of seribantumab to standard of care therapy in all three indications." (PMID 28725482, 2017). "Of those identified target genes, we selected HSPA6, histidine‐rich glycoprotein (HRG), ubiquitin D, prostaglandin E synthase (PTGES), tyrosine kinase (TXK), and MMP2 and measured those gene expressions in eight lung cancer cells 48 h after treatment with acRoots at 10 mg/mL." (PMID 32508044, 2020).
liver cancer (8 papers, 2015 to 2025). An epithelial or non-epithelial malignant neoplasm that arises from the liver. "By analysing a clinical cohort of patients, we found that HRG expression levels were significantly decreased in liver cancer tissues relative to normal liver tissues and that the risk of lung metastasis was higher in patients with low HRG expression levels." (PMID 37254661, 2023). "Furthermore, GSEA performed on liver cancer samples in the TCGA database implied that low expression of HRG was positively associated with NF-κB signaling." (PMID 32929358, 2020). "The HRG protein level of primary liver cancer tissue is significantly lower than that of normal liver tissue, and the HRG protein level of liver cancer tissue in patients with lung metastases is significantly lower than in patients without lung metastases." (PMID 37254661, 2023). "In this study, we reported that HCC cells reduce the secretion of HRG, regulate the recruitment and activation of neutrophils in the metastatic microenvironment and promote the production of NETs, thereby promoting liver cancer lung metastasis." (PMID 37254661, 2023). "Several cfRNAs specific to liver cancer are genes known to be specifically expressed in the liver (TF, HRG, CP, and FGA)." (PMID 35816095, 2022). "The regulatory effect of HRG on liver cancer lung metastasis was achieved by depleting Ly6G+ cells in a metastasis model relying on neutrophils in the pre‐metastatic microenvironment, this suggested an important role for neutrophils and NETs in early lung metastasis." (PMID 37254661, 2023). "Hepatocellular carcinoma cells reduce the secretion of histidine‐rich glycoprotein (HRG), regulate the recruitment and activation of neutrophils in the metastatic microenvironment and promote the production of neutrophil extracellular traps (NETs), thereby promoting liver cancer lung metastasis." (PMID 37254661, 2023).
COVID-19 (7 papers, 2021 to 2024). A disease caused by infection with severe acute respiratory syndrome coronavirus 2. "In contrast to the complement component proteins, histidine-rich glycoprotein (HRG, protein ID P04196) levels are heavily depleted in the severe COVID-19 group as compared to the other groups." (PMID 35842456, 2022). "From these proteins CRTAC1, IGLV3-1, HRG, HSPB1, LCP1, ITIH3, and APOA2 have all been identified as correlating with COVID-19 in other research, but to our knowledge, the rest are novel." (PMID 37308820, 2023). "In our serum proteomics data, the abundances of AHSG, FETUB, HRG, and KNG1 are found to be highly correlated in each of the sampled COVID-19 patients and are consistently higher in the survivors." (PMID 34226277, 2021). "Moreover, the plasma proteins HRG, FETUB, KNG1, LCAT, AHSG, and FN1 increase over time in abundance in the Munich cohort, thus suggesting their regulation during COVID-19 disease development." (PMID 34226277, 2021). "At present, we have no data on plasma levels of HRG or IAIPs in patients with COVID-19." (PMID 33841442, 2021).
hepatocellular carcinoma (6 papers, 2015 to 2024). A malignant tumor that arises from hepatocytes. "On the same vein, in vitro and in vivo studies have shown that HRG overexpression in hepatoma cell lines led to a decrease in cell proliferation, colony-forming ability, and tumor growth along with increased cancer cell apoptosis." (PMID 38469298, 2024). "Overexpression of HRG (histidine-rich glycoprotein) inhibits cell proliferation and increases apoptosis in hepatocellular carcinoma." (PMID 37511481, 2023). "In addition, the role of HRG in hepatocellular cancer appears dependent on its N-glycosylation status, especially that of Asn125, which may play a key competitive role in the interaction between HRG and heparin." (PMID 38272220, 2024). "HRG overexpression in Huh7 and MHCC-97H hepatoma cell lines led to decreased cell proliferation, colony-forming ability, and tumor growth, and increased cell apoptosis." (PMID 26336134, 2015).
melanoma (5 papers, 2015 to 2024). A malignant, usually aggressive tumor composed of atypical, neoplastic melanocytes. "Accordingly, CD36 deletion favors the growth of Lewis lung carcinoma (LL2) and B16F1 melanoma tumor cell implants, while the growth of the same tumors is impaired in syngeneic HRG null mice." (PMID 38469298, 2024). "HRG prevents the binding of S100A8/A9 to the B16-BL6 melanoma cell surface via the formation of the S100A8/A9 complex." (PMID 36142212, 2022). "HRG also inhibited the S100A8/A9-induced migration and invasion of A375 melanoma cells." (PMID 36142212, 2022).
glioma (4 papers, 2009 to 2022). A benign or malignant brain and spinal cord tumor that arises from glial cells (astrocytes, oligodendrocytes, ependymal cells). "Another study has reported that HRG suppresses glioma growth by modulating antitumor immunity through regulating leukocyte differentiation." (PMID 33553172, 2020). "To conclude, our investigation shows that expression of HRG in tumor cells can significantly inhibit the development of high-grade glioma and the mechanism is suggested to be through inhibition of tumor angiogenesis." (PMID 20046875, 2009). "We used the Ntv-a Arf-/- mice and induced tumors with RCAS-PDGF-B, a combination that mainly produces high-grade gliomas and analyzed how simultaneous expression of HRG would affect brain tumor development." (PMID 20046875, 2009). "We have investigated the effect of the antiangiogenic protein HRG on orthotopic PDGF-B induced glioma development in vivo using the Ntv-a Arf-/- mice that generate a high proportion of malignant tumors." (PMID 20046875, 2009). "STC2 could form a histidine-rich glycoprotein/stanniocalcin-2 (HRG/STC2) complex with HRG to regulate murine glioma growth via modulation of anti-tumor immunity." (PMID 35937984, 2022). "The colocalization of HRG and STC2 in gliomas may play a role for suppressing glioma growth by modulating tumor inflammation through monocyte infiltration and differentiation." (PMID 32498020, 2020).
pancreatic cancer (4 papers, 2016 to 2025). "In a pancreatic tumor mouse model, inhibition of macrophage recruitment using the CSF-1R inhibitors reduced metastatic spreading to liver, while increased macrophage conversion towards to the M2 phenotype by the loss of histidine-rich glycoprotein (HRG) increased metastatic spreading." (PMID 27191744, 2016). "IGF-1 and HRG by targeting the PI3K/AKT pathway could reduce pancreatic cancer cell sensitivity to gemcitabine or paclitaxel." (PMID 33768092, 2021). "Furthermore, platelets induce EMT in a transgenic mouse model of pancreatic cancer (RIP1-Tag2), with an even stronger effect in the absence of histidine-rich glycoprotein (HRG)." (PMID 39934930, 2025).
colorectal cancer (3 papers, 2017 to 2024). A primary or metastatic malignant neoplasm that affects the colon or rectum. "For example, Histidine-rich glycoprotein (HRG), which was abundant in the colorectal cancer plasma-derived exosomes, has been reported to promote the tumor migration of colorectal cancer patients." (PMID 38529947, 2024). "The HRG expression is connected with prognosis of colorectal cancer." (PMID 35922788, 2022).